RGS5 (regulator of G protein signaling 5)
Diseases named in the same sentence as RGS5 in open-access papers (continued):
Sharing a sentence is not in itself a finding about the gene and the disease.
aneurysm (1 paper, 2022). Bulging or ballooning in an area of an artery secondary to arterial wall weakening. "Similarly, the number of RGS5 and Fn positive cells was significantly reduced in the aortas of mice infused with angiotensin II (AngII), and it was nearly disappeared with aneurysm formation (Sham, 48.02±5.32% vs. AngII, 16.06±2.15% vs. AAA, 2.44±0.54%)." (PMID 35320283, 2022).
Arrhythmia (1 paper, 2021). Any cardiac rhythm other than the normal sinus rhythm. "Thus, Rgs5–/– seems to be an important determinant of arrhythmia vulnerability." (PMID 33815137, 2021).
arteriosclerosis (1 paper, 2014). A vascular disorder characterized by thickening and hardening of the walls of the arteries. "Consequently, pharmaceutical modulation of RGS5 activity by small molecule approaches, as has been shown for RGS4, may have great clinical relevance with respect to stimulating arteriogenesis or counteracting neointima formation during arteriosclerosis or in-stent restenosis." (PMID 24972930, 2014).
astrocytomas (1 paper, 2010). "The regulator of G protein signaling 5, RGS5, is over expressed in highly angiogenic astrocytomas and RGS5 expression is specifically up regulated in the vasculature of premalignant lesions." (PMID 20423517, 2010).
cholangiocarcinoma (1 paper, 2024). A carcinoma that arises from the intrahepatic biliary tree (intrahepatic cholangiocarcinoma) or from the junction, or adjacent to the junction, of the right and left hepatic ducts (hilar cholangiocarcinoma). "Fib-C3 cells were like the vascular cancer-associated fibroblasts (vCAFs) in the intrahepatic cholangiocarcinoma and exhibited high expression levels of ACTA2, RGS5, MYH11, and EPAS1." (PMID 39107908, 2024).
colon cancer (1 paper, 2022). "The fibroblasts and myofibroblasts were visualized by anti-human RGS5, decorin, podoplanin/gp36, CD36, α-SMA, and HHIP antibodies in colon mucosa and colon cancer tissues." (PMID 36463319, 2022). "Trajectory analysis and the gene expression patterns in single cells revealed that the expression of genes related to RGS5+ myofibroblasts’ structures and functions were not dramatically altered in colon cancer tissues in comparison to human colon mucosa." (PMID 36463319, 2022). "Gene profiling of single cells revealed that RGS5-expressing myofibroblasts, CXCL14-expressing fibroblasts and HHIP+ myofibroblasts showed extensive upregulation of extracellular matrix genes, including collagen genes, in colon cancer tissues." (PMID 36463319, 2022).
colorectal cancer (1 paper, 2022). A primary or metastatic malignant neoplasm that affects the colon or rectum. "To confirm the existence of CAFs with specific signatures, we applied immunofluorescence analysis and we detected the expression of PDGFRA (iCAFs marker) and RGS5 (mCAFs marker) in colorectal cancer." (PMID 35794563, 2022).
colorectal tumors (1 paper, 2023). "Accordingly, single-cell analyses of human colorectal tumors have revealed an abundant Rgs5-expressing subset, as well as increased expression of pericyte markers, such as Pdgfrb, Mcam, etc.." (PMID 38203319, 2023).
epilepsy (1 paper, 2025). A brain disorder characterized by episodes of abnormally increased neuronal discharge resulting in transient episodes of sensory or motor neurological dysfunction, or psychic dysfunction. "Taken together, our results suggest that a few neuronal subtypes, particularly the PVALB_RGS5, VIP_CRH, and SST_PENK subtypes, are closely associated with pediatric epilepsy." (PMID 40313715, 2025). "Among the identified neuronal subtypes, the three inhibitory neuronal subtypes PVALB_RGS5, VIP_CRH, and SST_PENK presented prominent transcriptomic alterations related to epilepsy." (PMID 40313715, 2025). "Among the inhibitory neurons, the number of interaction pairs tended to be greater in the epilepsy group than the control group, particularly for the PVALB_RGS5, VIP_CRH, and SST_PENK subtypes, and the VIP_CRH subtype showed the most significant increase." (PMID 40313715, 2025).
fibrosis (1 paper, 2014). the formation of excess fibrous connective tissue in an organ or tissue in a reparative or reactive process. "RGS5 deficient mice develop more severe liver injury following acute CCl4 exposure, and increased fibrosis after chronic CCl4 administration." (PMID 25290689, 2014).
HCMV infection (1 paper, 2020). "These outcomes demonstrated that HCMV infection, together with environmental risk factors, such as high levels of glucose and fat, regulated the expression level of RGS5 through methylation, thereby influencing the function of ECs." (PMID 32041970, 2020). "Therefore, RGS5 was selected as a target gene to investigate its role in the function of ECs, involving the interaction of HCMV infection with environmental risk factors." (PMID 32041970, 2020). "The evidence can be described as follows: First, HCMV infection or hyperglycemia and hyperlipidemia have the same downregulation effect on RGS5 caused by DNA hypermethylation, and they have synergistic influence, while opposite effects on the proliferation of ECs were noted." (PMID 32041970, 2020). "Notably, in the present research, we found that DAC reversed the low expression level of RGS5 caused by HCMV infection." (PMID 32041970, 2020). "Further analyses validated that the regulator of G-protein signaling 5 (RGS5) gene was downregulated in infected HUVECs and showed that HCMV infection promoted HUVEC proliferation, whereas hyperglycemia and hyperlipidemia inhibited HUVEC proliferation." (PMID 32041970, 2020). "The results of the current research demonstrated that HCMV infection promoted proliferation of ECs by downregulating the expression level of RGS5 via DNA hypermethylation." (PMID 32041970, 2020). "In summary, in this study, we provided evidence demonstrating that RGS5 was an important negative regulator of the proliferation of ECs following HCMV infection." (PMID 32041970, 2020). "Accordingly, RGS5 may represent a promising therapeutic target to prevent EH induced by HCMV infection." (PMID 32041970, 2020). "Our study first found that RGS5, a negative regulator of G protein-coupled receptors (GPCRs), was a target gene for dysfunction of ECs caused by HCMV infection, while that was not triggered by HG or ox-LDL." (PMID 32041970, 2020). "Furthermore, it was demonstrated that HCMV infection downregulated RGS5 by DNA hypermethylation, resulting in increased proliferation of ECs." (PMID 32041970, 2020). "Overall, our data demonstrated that HCMV infection could reduce the expression level of RGS5 by promoting hypermethylation, thereby increasing the proliferation of ECs." (PMID 32041970, 2020). "However, it is still elusive whether RGS5 can induce dysfunction of ECs in the context of HCMV infection." (PMID 32041970, 2020). "Thus, we further investigated whether HCMV infection induced RGS5 downregulation via DNA hypermethylation." (PMID 32041970, 2020). "Overexpression of RGS5 decreased the expression level of PCNA protein, suggesting that proliferation of ECs could be induced by HCMV infection via hypermethylation and downregulation of RGS5." (PMID 32041970, 2020). "Additionally, treatment with decitabine (DAC) and RGS5 reversed the effects of HCMV infection on HUVEC proliferation, but not triggered by hyperglycemia and hyperlipidemia." (PMID 32041970, 2020).
Hyperglycemia (1 paper, 2020). An increased concentration of glucose in the blood. "The mechanisms, in which hyperglycemia and hyperlipidemia induce proliferation of ECs, are complex and may involve various metabolic abnormalities; however, a low expression level of RGS5 owing to hypermethylation may not be one of these mechanisms." (PMID 32041970, 2020).
Hyperinsulinemia (1 paper, 2012). An increased concentration of insulin in the blood. "Under conditions of high circulating FFA and hyperinsulinemia, RGS5 deletion in obese mice significantly promoted the activation of PPARγ and SREBP-1c and led to exacerbated phenotypes, including increased liver weight and enhanced lipid droplet accumulation." (PMID 22272317, 2012). "RGS5 deficiency would likely involve enhanced Gαi-mediated signal pathway and be in charge of increased lipogenesis (mediated by DGAT1, DGAT2 and GPAT1) and decreased lipolysis (mediated by HSL and ATGL), under the conditions of hyperinsulinemia and high FFA, which can induce adipocyte hypertrophy." (PMID 22272317, 2012).
hyperparathyroidism (1 paper, 2022). Hyperfunction of the parathyroid glands resulting in the overproduction of parathyroid hormone. "The characteristic RGS5 protein and mRNA levels in hyperparathyroidism might be helpful in discovering the pathomechanism of hyperparathyroidism and novel therapeutic targets as well." (PMID 35681135, 2022). "In this study, we investigated the difference in the expressions of RGS5 in PHPT and SHPT models to shed light on the pathomechanism of hyperparathyroidism." (PMID 35681135, 2022).
hyperthyroidism (1 paper, 2022). Overactivity of the thyroid gland resulting in overproduction of thyroid hormone and increased metabolic rate. "Our results suggest that at the initial stage of transformation into tertiary hyperthyroidism, RGS5 expression follows an increasing trend at the nodular hyperplasia stage." (PMID 35681135, 2022).
interstitial lung disease (1 paper, 2021). A diverse group of lung diseases that affect the lung parenchyma. "Thus, further studies are needed to define the role of RGS5 in the development of interstitial lung disease, or for spontaneous or infection-triggered flare-ups." (PMID 34502263, 2021). "Targeting RGS5 might alleviate the severity of exacerbations in interstitial lung diseases." (PMID 34502263, 2021).
kidney cancer (1 paper, 2020). Primary or metastatic malignant neoplasm involving the kidney. "When we divided kidney cancer patients into subgroups based on their gender, location of the primary tumour and tumour status, the gene expression level reacts similarly to general results; aggressive tumours have a significantly lower expression level of RGS5." (PMID 32431860, 2020).
liver fibrosis (1 paper, 2014). "To investigate the role of RGS5 in mediating HSC activation and liver fibrosis, we induced liver injury (CCl4 model, as above) in Rgs5LacZ/LacZ mice to assess the changes in RGS5 cellular expression over time during injury." (PMID 25290689, 2014). "RGS5-mediated control of GPCR signaling in the liver is a novel mechanism by which HSC activation can be controlled, and a potential target of therapeutic intervention for liver fibrosis." (PMID 25290689, 2014).
lung diseases (1 paper, 2021). "Our systematic evaluation of RGS proteins of the R4 subfamily showed striking upregulation of RGS5 in human fibrosing lung disease samples." (PMID 34502263, 2021). "Gene profiling of the R4 subfamily showed increased RGS5 expression in human fibrosing lung disease samples." (PMID 34502263, 2021). "Despite all these limitations we believe there is sufficient evidence to say that RGS5 is a valuable therapeutic target for fibrosing lung disease." (PMID 34502263, 2021). "Thus, we hypothesized that RGS5 might play an important role in disease development and applied two independent animal models resembling the different stages of acute interstitial inflammation and fibrosing lung disease." (PMID 34502263, 2021). "The significant effects of RGS5 on the cellular and functional level might provide a rationale for a novel therapeutic approach to treat acute exacerbations in fibrosing lung diseases, without compromising anti-infection defense mechanisms." (PMID 34502263, 2021).
lung fibrosis (1 paper, 2021). "As a conclusion, loss of RGS5 preserves lung function and attenuates hyperinflammation in the acute phase of bleomycin-induced pulmonary fibrosis and LPS-induced lung injury." (PMID 34502263, 2021). "Next, we utilized the bleomycin mouse model, a well-established animal model for both acute inflammatory lung injury and lung fibrosis and investigated the longitudinal RGS5 expression." (PMID 34502263, 2021). "To investigate the role of RGS5 in vivo we examined the acute inflammatory response phase of pulmonary fibrosis utilizing RGS5-/- and WT at age 12–16 wk (equivalent to adult age in humans)." (PMID 34502263, 2021). "In contrast to RGS5 knockout, RGS2-/- mice displayed increased acute inflammation upon house dust mite and LPS inoculation and an augmented development of pulmonary fibrosis." (PMID 34502263, 2021). "Previous studies suggested that RGS2, RGS4 and RGS5 were protective against airway-hyperresponsiveness with modulated airway or bronchial contractility, while RGS2 was protective against bleomycin-induced lung fibrosis." (PMID 34502263, 2021).
lung injury (1 paper, 2021). "The absence of RGS5 resulted in less lung function deterioration and a blunted inflammatory response during the acute phase of bleomycin-induced and LPS-induced acute lung injury." (PMID 34502263, 2021).
metastatic tumors (1 paper, 2021). "The proportion of PDGFRA+ fibroblasts was significantly reduced in primary and lymph node metastatic tumors, whereas PSOTN+ and RGS5+ cells were significantly increased compared with adjacent normal tissues, reflecting the general remodeling of extracellular stroma in tumor tissues." (PMID 34185421, 2021).
neuroendocrine tumor (1 paper, 2021). "The transcriptomic landscape of 24,887 single cells was obtained and characterized as 10 cellular clusters, including epithelial, neuroendocrine tumor cells, T&NK cells, B cells, RGS5+ fibroblasts, POSTN+ fibroblasts, PDGFRA+ fibroblasts, endothelial, myeloid cells, and mast cells." (PMID 34185421, 2021).
ovarian tumor (1 paper, 2012). "Although RGS5 is a biomarker for tumor vasculature, we sought to understand whether RGS5 itself plays a pathogenic or protective role in ovarian tumor biology." (PMID 22792465, 2012). "We set out to clarify the extent to which RGS5 expression regulates tumor progression—whether it plays a pathogenic or protective role in ovarian tumor biology." (PMID 22792465, 2012).
parathyroid tumor (1 paper, 2022). "On the other hand, RGS5 has been found to be overexpressed in some of the parathyroid tumor cases associated with PHPT pathology." (PMID 35681135, 2022).
pheochromocytoma (1 paper, 2022). "Rgs5 is another selected marker, which is specific for only some of the identified populations, and has a high level of expression in pheochromocytoma." (PMID 36237181, 2022).
Pleural effusion (1 paper, 2025). The presence of an excessive amount of fluid in the pleural cavity. "For pleural effusion, BL and EP tumor cells had higher expression of mitochondria-associated genes, such as CO (cytochrome C oxidase), ND (NADH dehydrogenase), and ATP6, while LP cells expressed EMT-associated genes, such as YEATS4, MDM2, and RGS5." (PMID 39955556, 2025).
preeclampsia (1 paper, 2019). Preeclampsia is a hypertensive disorder of pregnancy that is characterized by new-onset hypertension with proteinuria presenting after 20 weeks of gestation, and depending on mild or severe forms may initially present with severe headache, visual disturbances, and hyperreflexia. "Some findings associated with preeclampsia in this study, such as MTHFR and RGS5 have been previously associated with preeclampsia, while maternal serum levels of TGFB2 and ABCA1 are altered in preeclampsia as well." (PMID 31557190, 2019).
primary hyperparathyroidism (1 paper, 2022). "The expression of RGS5 protein in 20 primary hyperparathyroidism (PHPT), 31 secondary hyperparathyroidism (SHPT), and 20 control cases were studied by immunohistochemistry (IHC)." (PMID 35681135, 2022).
SCC of the tongue (1 paper, 2019). "The findings indicate that RGS5 expression is related to tumor invasion and EMT in SCC of the tongue and that RGS5 may predict postoperative early lymph node metastasis." (PMID 31049219, 2019).
secondary hyperparathyroidism (1 paper, 2022). Overproduction of parathyroid hormone in response to influence external to the parathyroid glands. "The next step is to explore the significance of the difference in RGS5 expression between tertiary hyperparathyroidism and secondary hyperparathyroidism, which is helpful for the study of the pathogenesis of secondary hyperparathyroidism." (PMID 35681135, 2022).
tongue cancer (1 paper, 2019). A malignant neoplasm affecting the tongue. "In this study, we found that RGS5 expression in the invasive portion of tongue cancer was significantly higher in infiltrative type than in expansive type." (PMID 31049219, 2019).
Ventricular arrhythmia (1 paper, 2021). "Except that LPB was difficult to induce ventricular arrhythmia, Rgs5–/– greatly increased the induced S1–S2 interval at all sites of heart than that in WT group (P < 0.05)." (PMID 33815137, 2021).
ZIKV infection (1 paper, 2022). "RGS5 is one of the topmost affected proteins detected in HSerC after ZIKV infection." (PMID 35215967, 2022).